ANK2 (ankyrin 2)
Diseases named in the same sentence as ANK2 in open-access papers (continued):
Sharing a sentence is not in itself a finding about the gene and the disease.
neurodevelopmental disorder (3 papers, 2022 to 2025). A behavioral and cognitive disorder with onset during the developmental period that involves impaired or aberrant development of intellectual, motor, or social functions. "While brain specific Ank2 knockout mice do not exhibit impairments in memory and learning, the identified structural and connectivity changes recapitulate some of the morphological features observed in neurodevelopmental disorders, such as ASD." (PMID 35990955, 2022).
brain disorder (1 paper, 2023). A disease affecting the brain or part of the brain. "Ank2 has been implicated in various brain disorders, including ASD and epilepsy." (PMID 37321992, 2023).
neurodegenerative disease (1 paper, 2023). A disorder of the central nervous system characterized by gradual and progressive loss of neural tissue and neurologic function. "These proteins included Septin, Ankyrin-2, and Moesin, which have been previously implicated and studied in relation to neurodegenerative diseases, including AD." (PMID 36937050, 2023).
ANK2 also shares sentences with these, for which no sentence is quoted: Arrhythmia (12 papers); arrhythmogenic right ventricular cardiomyopathy (2); ischemia (2); Legionnaires' disease (2); Long QT syndrome 4 (2); melanoma (2); Obesity (2); Sinus bradycardia (2); 22q11.2 deletion syndrome (1); Adams-Oliver syndrome 5 (1); aortic stenosis (1); Asperger syndrome (1); Ataxia (1); AV block (1); Axenfeld-Rieger syndrome (1); bipolar disorder (1); cardiac conduction disease (1); cerebral malaria (1); colon cancers (1); death (1); dementia (1); depression (1); dilated cardiomyopathy (1); glioblastoma (1); hearing loss (1); heart failure (1); idiopathic ventricular fibrillation (1); iris coloboma (1); ischemic cardiomyopathy (1); malaria (1).
A further 18 diseases each share a sentence with ANK2 in 1 paper.